ERBB2 (erb-b2 receptor tyrosine kinase 2)
Diseases named in the same sentence as ERBB2 in open-access papers (continued):
Sharing a sentence is not in itself a finding about the gene and the disease.
breast cancer (continued). "To measure the amount of effort that a country X put into a gene Y, we divided the number of abstracts from country X which mentioned gene Y, by the number of papers published from country X. All of top 10 countries for breast cancer research put most of their effort into ESR1 and ERBB2." (PMID 27112211, 2016). "SUM149 cells were isolated from an inflammatory breast cancer patient whose tumor was defined as “triple negative” but which nevertheless in our hands expressed detectable basal levels of ERBB1, ERBB2, ERBB3, and ERBB4 by immuno-fluorescence of cells fixed in situ." (PMID 27379204, 2016). "Mechanistic studies demonstrated that t-DARPP was associated with the chaperone heat shock protein 90 (HSP90) and ERBB2 in a protein complex, suggesting that t-DARPP mediates trastuzumab resistance through regulation of ERBB2 receptor in trastuzumab-resistant breast cancer cells." (PMID 26872373, 2016). "Because the majority of erbB2-overexpressing (erbB2-positive) breast cancer cells express little or basal levels of EGFR, lapatinib mainly inhibits erbB2 kinase activity (intracellular domain) in erbB2-positive breast cancers." (PMID 26621843, 2016). "We have previously shown that short-term exposure to ethanol can stimulate the phosphorylation of p38 MAPK in breast cancer cells overexpressing ErbB2, but not in cells expressing low levels of ErbB2." (PMID 26655092, 2016). "ERBB2 overexpression in human breast cancer leads to invasive carcinoma but the mechanism is not clearly understood." (PMID 26899482, 2016). "The significance of MET amplification or deletion in the response to adjuvant or neoadjuvant therapy for ERBB2-positive breast cancer is not well established." (PMID 27576528, 2016). "Consistent with this, overexpression or knockdown of IRS1 and IRS2 had little or no affect upon ErbB2 action in both mouse and human mammary epithelial and breast cancer cells." (PMID 27765041, 2016). "For the other top-ranked miRNAs, five have no validated targets but have many predicted targets related to breast cancer such as AKT, AKT1, CCND1, EGFR1, ERBB2, SRC, PTEN which have been used as breast cancer biomarkers for prognosis, diagnosis, drug efficacy, and disease progression." (PMID 27833082, 2016). "Breast-cancer is heterogeneous and traditionally classified according to the expression of Estrogen-Receptor-alpha (NR3A1/ERα), Progesterone-Receptor (NR3C3/PR) and/or HER2, the ERBB2 gene product." (PMID 26894976, 2016). "The top two most mentioned genes in the breast cancer abstracts were ESR1 and ERBB2." (PMID 27112211, 2016). "To further explore the existence and diversity of ERBB2-positive GC cell lines, using the Cancer Cell Line Encyclopedia (CCLE), we found that among 37 tumor types, gastric cancer ranked second in ERBB2 mRNA expression (superseded only by breast cancer)." (PMID 26955870, 2016). "This suggests that TLK2 is frequently co-amplified with RPS6KB1, but not with other known amplified genes in breast cancer such as ERBB2, MYC, CCND1, and so on." (PMID 27694828, 2016). "It has been reported that overexpression of HRG, which occurs in a significant fraction of mammary tumors, contributes to the tumorigenic and invasive capacities of breast cancer cells, even in the absence of ErbB2 overexpression." (PMID 27351228, 2016). "In addition to the known role of ERBB2, research on other HER family genes in breast cancer is now ongoing." (PMID 26907936, 2016).
breast cancer (continued). "Here, using an in silico analysis of data from 2,096 breast tumours, we reveal a significant correlation between Gasdermin B (GSDMB) gene (located 175 kilo bases distal from ERBB2) expression and the pathological and clinical parameters of poor prognosis in HER2-positive breast cancer." (PMID 27462779, 2016). "Importantly, the combination of trastuzumab, pertuzumab and 3E10 demonstrates a greater ability to inhibit ErbB2 signaling and breast cancer cell growth compared with trastuzumab plus pertuzumab, suggesting that it might be a promising treatment for ErbB2-overexpressing breast cancer." (PMID 26999718, 2016). "Comparatively little is known about PIK3CA gene copy number alterations and clinical outcomes in breast cancer, irrespective of ERBB2 status." (PMID 27576528, 2016). "Palbociclib (= PD0332991) has been approved in 2015 by the FDA for the treatment of metastasized ER+, ERBB2-negative breast cancer in postmenopausal women in combination with Letrozole." (PMID 26943575, 2016). "HER2, also named ERBB2, is now considered as a key oncogene in breast cancer and colorectal cancer." (PMID 26701850, 2016). "To examine if HSP90 inhibition potentiates the antitumor efficacy of Trast-NG/DOX in vivo, we treated mice bearing xenografts of ErbB2-overexpressing BT-474 or ErbB2-low MCF-7 breast cancer cell lines with Trast-NGs/DOX with or without 17AAG." (PMID 26859680, 2016). "Furthermore, it has been reported earlier that hyaluronic acid stimulates the formation of a protein complex consisting of CD44, Hsp90, ErbB2 and ezrin, in TA3/St mammary carcinoma cells." (PMID 27029001, 2016). "Triple-negative breast cancer (TNBC) is a subtype of breast cancer that is lacking the expression ofestrogen receptor (ER), progesterone receptor (PR) and HER2 (ERBB2)." (PMID 26681397, 2015). "The resistance of cyclin D1−/−/MMTV-ErbB2 mice to ErbB2 driven mammary tumors is thought to be dependent on a complete absence of PI mammary cells in cyclin D1-null mice." (PMID 25940700, 2015). "This negative result concurs with the clinical pathology report for the original breast cancer biopsy specimen, where ERBB2 gene was not amplified according to FISH." (PMID 25970776, 2015). "ErbB-2 (avian erythroblastosis oncogene B) or HER2/neu is a member of the epidermal growth factor receptor (EGFR) family and plays an important role in the pathogenesis of breast cancer." (PMID 25665066, 2015). "Our recent report showed that combined treatment with lapatinib, a dual inhibitor of EGFR and ErbB2/HER2, and imatinib, a c-ABL inhibitor, resulted in synergistic growth inhibition in a panel of EGFR/ErbB2-expressing breast cancer cells including the TNBC cell line MDA-MB-468." (PMID 25883211, 2015). "In breast cancer for instance, patients with tumors that are estrogen receptor (ER) and epidermal growth factor receptor (ErbB2) negative are less responsive to hormone based treatment than those possessing active receptors." (PMID 25965340, 2015). "Expression of miR-21 is significantly higher in ERα positive, ErbB2 negative, and PR positive than in ERα negative, ErbB2 positive, and PR negative breast cancers." (PMID 25705321, 2015). "For example, ERBB2 (HER2) copy number amplification in NSCLC does not predict TKI response as it does in breast cancer." (PMID 26474073, 2015). "Breast cancer is a highly heterogeneous disease, classified by stage, size, morphology and the presence of receptors such as estrogen receptor, progesterone receptor or ERBB2/HER2." (PMID 25596742, 2015). "In line with the result we report here, signaling mechanisms are known to drive transcription and upregulation of ERBB2 in breast cancer absent any copy number gain." (PMID 25970776, 2015).
breast cancer (continued). "Increasing numbers of genes involved in breast cancer have been found, including Ets-1 (E-twenty-six-1), PKC (protein kinase C), CEP4 (CDC42 effector protein 4), Her2 (erb-b2 receptor tyrosine kinase 2), ALDH1 (aldehyde dehydrogenase 2), FOXA1 (forkhead box A1) and HOXD10 (homeobox D10)." (PMID 25739083, 2015). "The risk of recurrence is higher for ERBB2 positive breast cancers than for ERBB2 negative breast cancers." (PMID 25964777, 2015). "The observed focal amplifications of the ERBB2 genomic region and the increase in gene expression levels of the genes herein suggest that a proportion of CHEK2*1100delC breast cancers could be related to the ERBB2/Her2Neu intrinsic subtype." (PMID 26553136, 2015). "Our observation can generate a hypothesis that ERBB2 and S100A7A-mediated MMP13 expression can contribute to the subtype-specific spatial growth patterns in breast cancer." (PMID 26669540, 2015). "Although ERBB2 overexpression has been correlated with survival in other tumor types, such as breast cancer, there has been no previous report of this correlation in UC." (PMID 26039708, 2015). "Even though the significance of this finding was not clear, it was proposed that these miRNAs may be involved in the regulation of their host genes that are found overamplified in breast cancer (e.g., ERBB2/HER2)." (PMID 26561834, 2015). "Moreover, overexpression of miR-125b inhibited cell growth and reduced migration and invasion in breast cancer cells through suppression of ERBB2 (erythroblastic leukemia viral oncogene homolog 2) and ERBB3 in breast cancer cells." (PMID 25605244, 2015). "In spite of the clinical efficiency of lapatinib in breast cancer patients, some ERBB2-expresing tumors are not responsive to this treatment and some patients that do initially respond, acquire lapatinib resistance." (PMID 25596742, 2015). "Furthermore, miR-125b was found to suppress the oncoproteins MUC1, ERBB2, and ERBB3, inhibiting the growth of breast cancer cells." (PMID 26693202, 2015). "In addition, a positive-feedback loop, involving HA, PI3K, and ErbB2, augments MDR1 expression and regulates drug resistance in breast cancer cells." (PMID 25999946, 2015). "Yet transgenic rats overexpressing rat ERBB2 in the mammary gland developed mammary tumors only in males and not in females, suggesting that the development of tumors was androgen dependent." (PMID 25928046, 2014). "Additionally characterized on the breast cancer cells are three important receptors: estrogen receptor (ER), progesterone receptor (PR), and ERBB2 (Her2), and the presence of these receptors can influence prognosis and treatment." (PMID 24918944, 2014). "The endogenous p95 ErbB2 in BT474 breast cancer cells does not respond to EGF as the full-length ErbB2, but instead gets phosphorylated and activated in response to ErbB3 and ErbB4 ligand heregulin." (PMID 24709902, 2014). "A Phase II trial of PD0332991 was performed in 37 patients with advanced breast cancer (mostly ER-positive ERBB2-negative), pretreated with chemotherapy." (PMID 25349887, 2014). "In breast cancer in particular, FISH assays for the assessment of HER2 (ERBB2) gene status on chromosome (chr) 17q12 are used as in vitro diagnostic devices (IVD), based on the well established clinical utility of this marker for selecting patients who will benefit from trastuzumab treatment." (PMID 25098819, 2014). "In erbB2+ breast cancer tissues, preferential phosphorylation of erbB3, but not EGFR, has been observed." (PMID 24886126, 2014). "Furthermore, expression and activation of ERBB2 in MCF-7 cells and MDA-MB-435 breast cancer cells induces invasion through a pathway that involves PKCα." (PMID 24599099, 2014). "The basal levels of MMP-1 and MMP-9 are increased in various breast cancer cells, including MCF7, in response to heregulin-β1 via activation of MAPK/ERK pathway and overexpression of Ets1 in ErbB2 expressing breast cancer cells increases the expression of MMP-1." (PMID 24709902, 2014).
breast cancer (continued). "We showed as expected that both lapatinib as well as the irreversible ErbB2 inhibitor, PD168393 could induce apoptosis and inhibit cell growth in ErbB2 positive lung and breast cancer cell lines." (PMID 25238247, 2014). "Triple-negative breast cancer (TNBC) is an aggressive breast cancer subtype defined by the lack of ER, progesterone receptor and human epidermal growth factor receptor 2 (ErbB2)." (PMID 25606587, 2014). "In an ErbB2 overexpressing breast cancer cell line, SKBR3, flotillin-1 and flotillin-2 partially colocalized with ErbB2 at the plasma membrane and formed a complex with ErbB2 and Hsp90 which is an important factor for the stabilization of ErbB2 at the plasma membrane." (PMID 24709906, 2014). "Most metastatic breast cancers show expression of either EGFR or erbB2, whereas upregulation of both is not typical." (PMID 24886126, 2014). "ERBB2/HER2 amplification is a marker of aggressive disease, although the development of the trastuzumab monoclonal antibody targeting the ERBB2/HER2 receptor has revolutionised breast cancer treatment regimes, leading to improved survival rates." (PMID 25269082, 2014). "Lastly, we show that the CEA-specific IgGs no longer bind to ErbB2/HER2 overexpressing breast cancer SKBR3 cells." (PMID 24586053, 2014). "ErbB2 positive breast cancer patients are treated with combination therapy consisting of chemotherapy and trastuzumab (Herceptin), a humanized monoclonal antibody that targets the extracellular NH2-terminal domain of ErbB2." (PMID 24709902, 2014). "Our study found that DF extract alone had no significant growth inhibitory effect on various EGFR/ERBB2-amplified gastroesophageal and breast cancer cell lines in vitro." (PMID 24587811, 2014). "We also found that PHLDA1 is significantly less expressed in ErbB2 negative tumors compared with the ErbB2 positive breast cancers." (PMID 25238247, 2014). "Overall, in dose-dependent drug sensitivity test, DF, as a single agent, did not significantly inhibit the growth of EGFR/ERBB2-amplified gastroesophageal and breast cancer cell lines even at supra-pharmacological doses." (PMID 24587811, 2014). "Triple-negative breast cancer (TNBC) is a special subtype of breast cancer, which is defined as the absence of estrogen and progesterone receptor expression as well as ERBB2 amplification." (PMID 24529079, 2014). "Furthermore, in a study on methylation in breast cancer and breast cancer molecular subtypes it was shown that RASSF1A is hypermethylated in HER2 positive breast tumors (ERBB2 and luminal B)." (PMID 24093668, 2013). "Closely parallel to our observations of the negative regulation of BST2 in breast cancer, AP2 is involved in the repression of promoter sequences of the oncogene, ERBB2, evident as an inverse correlation between AP2 and ERBB2 immunolocalization in archival tumor specimens." (PMID 23840623, 2013). "Breast cancer therapies targeted against ErbB2, although very specific, do not apply to all patients as some cells become resistant." (PMID 23389114, 2013). "For example, we also found the correlation of ERBB2 and MUC1 with breast cancer prognosis." (PMID 24073403, 2013). "Three of the four cell lines tested exhibited increased colony formation in response to Ets1 expression; however, the BT-474 cell line, the only one of these ERα positive, luminal breast cancer lines that expresses ErbB2, did not." (PMID 23874775, 2013). "In MDA-MB-453 breast cancer cells that do not express ERα, AR activates ERBB2 signaling by direct androgen-dependent induction of WNT7B and ERBB3 expression." (PMID 23593223, 2013). "In accord with these mouse model data, we found that unlike the basal subtype, ErbB2+ human breast cancers rarely involve aberrant activation of Wnt signaling." (PMID 24265712, 2013). "In ERα negative breast cancer, ERBB2 overexpression significantly correlates with high AR and ERBB3 expression." (PMID 23593223, 2013).
breast cancer (continued). "Recently, we have shown that knockdown of filamin-A in melanoma C8161 cells reduced metastasis in xenograft mouse models, and that filamin-A inhibition reduced the mobility and invasiveness of breast cancer cell lines that do not over-express ErbB2 in vitro." (PMID 23388158, 2013). "We hypothesise that amino acid variant interactions could have incremental effects on the cat erbB-2 protein structure, function, and therapeutics, as it is known that the CR2 domain plays an important role in human breast cancer treatment." (PMID 24386251, 2013). "Our microarray data revealed no obvious difference in ErbB2 mRNA levels in wild-type versus polyQ-huntingtin mammary tumours (FC = −1.19; p-value = 8.57 × 10−2)." (PMID 23300147, 2013). "ErbB2-positive breast cancer cells lacking LKB1 displayed increased expression of several enzymes and transporters that support glycolysis, and both glycolytic flux and overall lactate production were enhanced in LKB1-deficient breast cancer cells." (PMID 24280377, 2013). "We would like to emphasise that the recurrent occurrence of low erbB-2 expression levels in cat mammary tumours, suggests the cat mammary neoplasias as a valuable model for erbB-2 negative HBC." (PMID 24386251, 2013). "ErbB2 is a receptor tyrosine kinase overexpressed in 25% to 30% of human breast cancers, drives mammary tumor formation, and defines the HER2 subtype, a poor-prognosis form of breast cancer." (PMID 24280377, 2013). "This is consistent with the role of high VRK2 level in breast cancer, in which also correlates with tumors having a better prognosis, those that are estrogen and progesterone receptor positive and ERBB2 negative." (PMID 24079673, 2013). "On the other hand, 29 of 33 breast cancer cell lines present in the major cluster were of the luminal-type, and all cell lines except SUM185 exhibited either one of the hormone receptor proteins or showed ERBB2 protein expression." (PMID 23601657, 2013). "A second group of breast cancer patients is characterized by an amplification of chromosome region 17q12-21, leading to the overexpression of the epidermal growth factor receptor 2, ERBB2/HER2/neu." (PMID 23192763, 2013). "ERBB2/HER2, best known for its role in breast cancer tumorigenesis, can be targeted by two types of pharmacological manipulation: antibody therapy against the extracellular receptor domain and small molecule compounds against the intracellular tyrosine kinase domain." (PMID 23630663, 2013). "The growth of both ERBB2/Neu-induced breast cancer cells with increased expression of PGC-1α (α-1.1) and controls was ablated in the absence of glutamine, illustrating that ERBB2/Neu-induced breast cancer cells require glutamine for their growth." (PMID 24304688, 2013). "Likewise, activation of PAR1 by thrombin induces persistent EGFR and ErbB-2 transactivation, sustained p42/p44 MAPK signalling, and invasion in breast cancer cells." (PMID 24215724, 2013). "In addition, these authors demonstrated that PAR1-stimulated EGFR and ErbB-2 transactivation sustains p42/p44 MAPK signalling and promotes breast carcinoma cell invasion." (PMID 24215724, 2013). "Consistent with our results, miR-125b did not induce ErbB2/HER2 down-regulation in either prostate cancer cells or breast cancer cells including SKBr3 cells in other reports." (PMID 22523546, 2012). "ErbB2 (HER2/neu), a member of the EGFR family of receptor tyrosine kinases, first attracted attention after the discovery that this gene is amplified and over-expressed in a high percentage of breast cancers." (PMID 22912742, 2012). "This was observed in both breast cancer and GBM datasets and leaves open the possibility that selection of well-known drivers such as ERBB2 and EGFR may be synergistically acting on altered metabolic processes abrogated by co-altered, nearby metabolism genes." (PMID 23383675, 2012).